PCSEAT (prostate cancer expressed EZH2 associated transcript)
Synonyms: PRCAT38
Gene: Long non-coding RNA gene on chromosome 21 (41,580,475 to 41,582,887, forward strand). Ensembl gene ENSG00000286027.
Diseases named in the same sentence as PCSEAT in open-access papers:
PCSEAT is named in the same sentence as 4 diseases in open-access papers, as found by Europe PMC text mining. Sharing a sentence is not in itself a finding about the gene and the disease.
PCSEAT shares sentences with these, for which no sentence is quoted: prostate carcinoma (3 papers); benign prostate hyperplasia (1); cancer (1); tumor (1).